MPND (MPN domain containing)
Description:
Probable protease (By similarity). Acts as a sensor of N(6)- methyladenosine methylation on DNA (m6A): recognizes and binds m6A DNA, leading to its degradation. Binds only double strand DNA (dsDNA) in a sequence-independent manner (By similarity).
Synonyms: FLJ14981
Tractability: PROTAC: ubiquitination databases record sites on it.
Gene: Protein-coding gene on chromosome 19 (4,343,527 to 4,360,086, forward strand). Ensembl gene ENSG00000008382.
Subcellular location (Human Protein Atlas): Nucleoli rim; Nucleoplasm
Gene Ontology:
Molecular function: protein binding; metallopeptidase activity; polyubiquitin modification-dependent protein binding; metal-dependent deubiquitinase activity; peptidase activity
Biological process: double-strand break repair
Cellular component: BRCA1-A complex; BRISC complex
Genetic constraint (gnomAD): Loss-of-function variants: 56 observed, 52.01 expected, observed/expected ratio (o/e) 1.08, 90% interval 0.87 to 1.35. The synonymous counts are far from expectation, so gnomAD's model fits this gene poorly and the ratio says little. Missense variants: 671 observed, 570.9 expected, observed/expected ratio (o/e) 1.18, 90% interval 1.1 to 1.25. Synonymous variants: 323 observed, 254.02 expected, observed/expected ratio (o/e) 1.27, 90% interval 1.16 to 1.39.
Homologues: Orthologues: chimpanzee MPND (99% identical), macaque MPND (88% identical), pig MPND (88% identical), mouse Mpnd (83% identical), rat Mpnd (83% identical), dog MPND (81% identical), guinea pig MPND (69% identical), tropical clawed frog mpnd (61% identical), zebrafish mpnd (57% identical). Paralogues in human: MYSM1 (25% identical), SMARCC2 (17% identical), SMARCC1 (15% identical).
Diseases named in the same sentence as MPND in open-access papers:
MPND is named in the same sentence as 4 diseases in open-access papers, as found by Europe PMC text mining. Sharing a sentence is not in itself a finding about the gene and the disease. The quoted sentences say what the papers report.
gastric cancer (4 papers, 2015 to 2022). A primary or metastatic malignant neoplasm involving the stomach. "The remaining prognostic genes such as OLFML2B, RAI14, SERPINE1, and MPND were also reported to be dysregulated and associated with poor prognosis in gastric cancer." (PMID 32908579, 2020). "MPND was reported to be dysregulated and associated with poor prognosis in gastric cancer." (PMID 34104084, 2021).
cancer (2 papers, 2015 to 2021). A tumor composed of atypical neoplastic, often pleomorphic cells that invade other tissues. "Among the 54 cancer-related genes, DGKG, MPND, NPIPB5, PRR21, SGSM1, and TRIM67 displayed frameshift mutations." (PMID 34104084, 2021). "In addition, the present study revealed 6 cancer-related genes, DGKG, MPND, NPIPB5, PRR21, SGSM1, and TRIM67, which showed novel frameshift mutations." (PMID 34104084, 2021).
MPND also shares sentences with these, for which no sentence is quoted: retinoblastoma (2 papers); tumor (1).